SHISA6 (shisa family member 6)
Description:
Involved in maintenance of high-frequency synaptic transmission at hippocampal CA3-CA1 synapses. Regulates AMPA-type glutamate receptor (AMPAR) immobilization at postsynaptic density keeping the channels in an activated state in the presence of glutamate and preventing synaptic depression. May play a role in self-renewal and differentiation of spermatogonial stem cells by inhibiting canonical Wnt signaling pathway.
Synonyms: FLJ45455
Tractability: Antibody: UniProt predicts a signal peptide or a membrane-spanning region; the Human Protein Atlas places it where antibodies can reach. PROTAC: its protein half-life has been measured.
Gene: Protein-coding gene on chromosome 17 (11,241,213 to 11,564,063, forward strand). Ensembl gene ENSG00000188803.
Subcellular location: Membrane; Postsynaptic density
Subcellular location (Human Protein Atlas): Nucleoplasm; Plasma membrane
Gene Ontology:
Molecular function: protein binding; ionotropic glutamate receptor binding; PDZ domain binding
Biological process: excitatory chemical synaptic transmission; negative regulation of canonical Wnt signaling pathway; regulation of AMPA glutamate receptor clustering; regulation of short-term neuronal synaptic plasticity; spermatogenesis; postsynaptic neurotransmitter receptor diffusion trapping
Cellular component: AMPA glutamate receptor complex; asymmetric, glutamatergic, excitatory synapse; dendritic spine membrane; postsynaptic density; postsynaptic membrane; glutamatergic synapse; membrane; postsynaptic density membrane
Genetic constraint (gnomAD): Loss-of-function variants: 19 observed, 40.68 expected, observed/expected ratio (o/e) 0.47, 90% interval 0.32 to 0.69. The upper end of that interval is the gene's LOEUF score, 0.69, which puts it in group 2 of 6, group 1 being the genes least tolerant of losing a copy. Missense variants: 649 observed, 694.14 expected, observed/expected ratio (o/e) 0.93, 90% interval 0.88 to 1. Synonymous variants: 374 observed, 318.15 expected, observed/expected ratio (o/e) 1.18, 90% interval 1.08 to 1.28.
Homologues: Orthologues: chimpanzee SHISA6 (99% identical), macaque SHISA6 (99% identical), dog SHISA6 (95% identical), rabbit SHISA6 (95% identical), rat Shisa6 (94% identical), mouse Shisa6 (89% identical), tropical clawed frog shisa6 (66% identical), zebrafish shisa6 (25% identical). Paralogues in human: SHISA7 (28% identical), SHISA9 (23% identical), SHISA8 (19% identical).
Diseases named in the same sentence as SHISA6 in open-access papers:
SHISA6 is named in the same sentence as 9 diseases in open-access papers, as found by Europe PMC text mining. Sharing a sentence is not in itself a finding about the gene and the disease. The quoted sentences say what the papers report.
Anxiety (1 paper, 2021). Intense feelings of nervousness, tension, or panic often arise in response to interpersonal stresses. "Baseline behavioral assessments showed increased anxiety-like behaviors (decreased center time in open-field test; *, p = 0.011) and anhedonia (decreased sucrose preference; *, p = 0.040) when Shisa6 is overexpressed in D1-MSNs of male mice." (PMID 34253865, 2021). "In summary, we found Shisa6 expression is increased in D1-MSNs of Sus mice and increases excitability of neurons, which modulates anxiety- and depression-like behaviors in mice." (PMID 34253865, 2021). "Shisa6 is specifically located in excitatory synapses of D1-MSNs and increases excitability of neurons, which promotes anxiety- and depression-like behaviors in mice." (PMID 34253865, 2021). "To investigate whether Shisa6 can directly modify depression- and anxiety-like behaviors in vivo, we overexpressed or knocked-down the Shisa6 gene in D1-MSNs and performed several behavioral assays." (PMID 34253865, 2021). "Furthermore, from D1 vs D2 comparisons, we also found Shisa6 in the D1 Sus DEG list, which is associated with highly relevant GO terms such as MDD, bipolar disorder, and anxiety in a GWAS database." (PMID 34253865, 2021).
autoimmune disease (1 paper, 2025). A disorder resulting from loss of function or tissue destruction of an organ or multiple organs, arising from humoral or cellular immune responses of the individual to their own tissue constituents. "We examined the association of the PRS-RCDII, derived from three non-HLA genetic variants, namely rs2041570 on chromosome 7p14.3 (FAM188B), rs7324708 on chromosome 13q22.1 (KLF12), and rs205047 on chromosome 17p12 (SHISA6), with 27 unique phecodes related to autoimmune diseases." (PMID 40900534, 2025).
depression (1 paper, 2021). "Interestingly, Shisa9, which has opposite functions to Shisa6 at glutamatergic synapses, was identified as a highly associated gene for major depression in recently published large-scale GWAS studies." (PMID 34253865, 2021). "Results from this study revealed that Shisa6 contributes to the cell-type-specific molecular genetic pathogenesis of depression." (PMID 34253865, 2021). "Here we report a circuit- and cell-type specific molecular target for depression, Shisa6, recently defined as an AMPAR component, which is increased only in D1-MSNs in the NAc of susceptible mice." (PMID 34253865, 2021). "Interestingly, Shisa9 was recently identified as a gene related to major depression by large-scale GWAS and is known to counteract Shisa6." (PMID 34253865, 2021). "Taken together, Shisa6 may be a critical link of dopamine and glutamatergic systems in the reward circuitry, and a promising molecular target for intervention during depression pathogenesis." (PMID 34253865, 2021). "Cell-type and circuit-specific action of Shisa6, which directly modulates excitatory synapses that convey aversive information, identifies the protein as a potential rapid-antidepressant target for aberrant circuit function in depression." (PMID 34253865, 2021). "In the future, exploring the Shisa6+ D1-MSN population and their connectivity may provide valuable insight on mechanisms of depression." (PMID 34253865, 2021). "The regulation of Shisa6, an AMPAR regulatory protein, may act as a potential therapeutic target for treating depression." (PMID 34253865, 2021).
Huntington disease (1 paper, 2022). Huntington disease (HD) is a rare neurodegenerative disorder of the central nervous system characterized by unwanted choreatic movements, behavioral and psychiatric disturbances and dementia. "We also report a downregulation of proteins involved in glutamatergic signalling in the hippocampus of Huntington’s disease mice: SHISA6, responsible for AMPA-type glutamate receptor immobilization at postsynaptic density, and glutamate receptor 1 (GRIA1, AMPA type)." (PMID 36523271, 2022). "We also reported differential expression of proteins involved in glutamate signalling: protein shisa-6 (SHISA6) and neuronal pentraxin receptor (NPTXR) were both downregulated in Huntington’s disease mice and regulate AMPA immobilization and synaptic clustering." (PMID 36523271, 2022).
Obesity (1 paper, 2025). Accumulation of substantial excess body fat. "Three of the common DEGs altered by obesity in all NVU cell types (Slc44a5, Gria1, and Shisa6) play a key role in neurotransmission." (PMID 41310161, 2025).
SHISA6 also shares sentences with these, for which no sentence is quoted: Alzheimer disease (1 paper); bipolar disorder (1); myopia (1); Stroke (1).